ARVCF (ARVCF delta catenin family member)
Description:
Contributes to the regulation of alternative splicing of pre-mRNAs.
Tractability: Antibody: its Gene Ontology location is reachable by antibodies, with medium confidence; the Human Protein Atlas places it where antibodies can reach. PROTAC: ubiquitination databases record sites on it; its protein half-life has been measured.
Gene: Protein-coding gene on chromosome 22 (19,969,892 to 20,016,823, reverse strand). Ensembl gene ENSG00000099889.
Subcellular location: Cell junction, adherens junction; Nucleus; Cytoplasm
Subcellular location (Human Protein Atlas): Cell Junctions; Plasma membrane
Gene Ontology:
Molecular function: cadherin binding; protein binding
Biological process: RNA splicing; cell adhesion; cell-cell adhesion
Cellular component: adherens junction; cell junction; cytoplasm; nucleus; plasma membrane
Genetic constraint (gnomAD): Loss-of-function variants: 66 observed, 78.5 expected, observed/expected ratio (o/e) 0.84, 90% interval 0.69 to 1.03. The upper end of that interval is the gene's LOEUF score, 1.03, which puts it in group 4 of 6, group 1 being the genes least tolerant of losing a copy. Missense variants: 1,469 observed, 1,284.3 expected, observed/expected ratio (o/e) 1.14, 90% interval 1.1 to 1.19. Synonymous variants: 653 observed, 559.64 expected, observed/expected ratio (o/e) 1.17, 90% interval 1.09 to 1.25.
Homologues: Orthologues: chimpanzee ARVCF (99% identical), macaque ARVCF (98% identical), dog ARVCF (94% identical), guinea pig ARVCF (94% identical), pig ARVCF (92% identical), mouse Arvcf (92% identical), rabbit ARVCF (86% identical), rat Arvcf (86% identical), tropical clawed frog arvcf (69% identical), zebrafish arvcfb (67% identical), zebrafish arvcfa (41% identical). Paralogues in human: CTNND1 (46% identical), CTNND2 (39% identical), PKP4 (36% identical), PKP3 (21% identical), PKP1 (21% identical), PKP2 (21% identical).
Diseases named in the same sentence as ARVCF in open-access papers:
ARVCF is named in the same sentence as 28 diseases in open-access papers, as found by Europe PMC text mining. Sharing a sentence is not in itself a finding about the gene and the disease. The quoted sentences say what the papers report.
schizophrenia (5 papers, 2015 to 2023). A major psychotic disorder characterized by abnormalities in the perception or expression of reality. "Although an association of ARVCF with schizophrenia has been previously reported, whether this gene is associated with other addictive or psychiatric disorders has not been reported yet." (PMID 38025780, 2023). "Interestingly, these genes have previously been associated with human social disorders such as autism for SEZ6L and schizophrenia for ARVCF." (PMID 30416887, 2018). "Some have been associated with neurodevelopmental disorders: schizophrenia (DIXDC1, ARVCF, MAGI2, ZIC2), ADHD (attention deficit/hyperactivity disorder) (TCERG1L), movement disorders (NOL3, TP53INP2), Huntington’s disease (H2AFY2, AGPAT1), Parkinson’s disease (LMX1B), and autism (PLXNA4, WNT2)." (PMID 25748564, 2015). "Three of these loci (MTHFR, DAOA, ARVCF) had never been implicated by a schizophrenia GWA study." (PMID 31455759, 2019). "Three (MTHFR, DAOA, ARVCF) of these loci had not been reported in a schizophrenia GWA study within the Asian or Caucasian populations." (PMID 31455759, 2019). "Five of these top eight LD-independent loci (MTHFR, PDE4B, DAOA, ARVCF, TRAM1L1/NDST3) were not located within risk loci identified in the largest schizophrenia GWA study produced by the PGC and three loci (MTHFR, DAOA, ARVCF) had never been implicated by a schizophrenia GWA study." (PMID 31455759, 2019).
Velocardiofacial syndrome (3 papers, 2010 to 2022). "Note that ARVCF (Armadillo Repeat gene deletes in Velocardiofacial syndrome, GeneID 421) is adjacent to COMT on chromosome 22, so it is included in the GRAIL gene set." (PMID 20102619, 2010).
nicotine dependence (2 papers, 2023 to 2024). Physical and psychological dependence on nicotine. "Our previous research identified a novel functional variant, rs148582811, located in Armadillo Repeat gene deleted in Velo-Cardio-Facial syndrome (ARVCF), which regulates ARVCF expression and plays an important role in nicotine dependence." (PMID 39429782, 2024). "Although numerous susceptibility loci are nominated for nicotine dependence (ND), no report showed any association of ARVCF with ND." (PMID 38025780, 2023).
prostate carcinoma (2 papers, 2012 to 2020). A carcinoma that arises from epithelial cells of the prostate gland. "Some of the genes associated with these 16 sites included PLEKHA7, AP1M2, ATP9A, and ARVCF known to be downregulated in breast and prostate cancer (data not shown), as well as other cancers." (PMID 32503656, 2020).
alcohol dependence (1 paper, 2024). Physical and psychological dependence on alcohol. "Our gene-based association tests showed significant correlations of ARVCF expression in the nucleus accumbens (NAc) basal ganglia (pECS = 0.019, pGATES = 0.027) and anterior cingulate cortex (pECS = 0.015) with alcohol dependence." (PMID 39429782, 2024). "Our gene-level EMIC analysis indicated a causal relationship between ARVCF expression in the NAc and alcohol dependence (β = 0.013, SE = 0.006, p = 0.039)." (PMID 39429782, 2024). "ARVCF was significantly associated with alcohol dependence in both gene-based association test and EMIC analysis." (PMID 39429782, 2024). "Taken together, we first discovered that ARVCF is a susceptible gene for alcohol use, and then we confirmed that ARVCF plays an important role in alcohol dependence in mice." (PMID 39429782, 2024). "We also performed EMIC analysis to infer whether ARVCF expression in the brain causally associated with alcohol dependence." (PMID 39429782, 2024). "In conclusion, our study identifies ARVCF as a susceptibility gene for alcohol dependence." (PMID 39429782, 2024). "Transcript-level EMIC analysis showed that ARVCF transcript expression in the amygdala (p < 0.05) may also be implicated in alcohol dependence." (PMID 39429782, 2024). "Future studies that focus on unraveling the underlying mechanisms of how ARVCF controls alcohol dependence could be valuable." (PMID 39429782, 2024). "Besides, transcript-based analysis further associated ARVCF transcript expression in the cerebellar hemisphere (pGATES = 0.010), substantia nigra (pGATES = 0.028), and cervical spinal cord (pGATES = 0.030) with alcohol dependence." (PMID 39429782, 2024). "Future research should aim to elucidate the mechanisms of the ARVCF gene in alcohol dependence and other psychiatric conditions." (PMID 39429782, 2024). "Our findings highlight the significant role of ARVCF in alcohol dependence, particularly in its expression within the NAc, a region central to dopamine release and reward-seeking behavior." (PMID 39429782, 2024). "Together, our combined human genetic and animal studies indicate that ARVCF plays a crucial role in alcohol dependence." (PMID 39429782, 2024). "The central conclusion of this study underscores the essential role of ARVCF, a member of the p120ctn protein family, in regulating behaviors related to alcohol dependence." (PMID 39429782, 2024). "These genetic data-based analyses collectively establish that ARVCF plays an important role in alcohol dependence." (PMID 39429782, 2024). "To further validate the role of the ARVCF gene in alcohol dependence, we then conducted an alcohol-induced conditioned place preference (CPP) test in CRISPR-Cas9-generated Arvcf knockout (KO) mice." (PMID 39429782, 2024). "Future studies investigating the role of ARVCF in the mesocorticolimbic brain reward circuit and its involvement in alcohol dependence may yield further valuable insights." (PMID 39429782, 2024). "Moreover, leveraging extensive European alcohol dependence data, our gene association tests and EMIC analysis showed that ARVCF expression in the nucleus accumbens was significantly associated with alcohol dependence." (PMID 39429782, 2024).
alcohol-related disorders (1 paper, 2024). Disorders related to or resulting from abuse or mis-use of alcohol. "ARVCF and its polymorphic sites, such as rs2531698 and rs116570619 identified in this study, may play an important role in alcohol-related disorders and could be valuable for diagnostic and preventative measures of related disorders." (PMID 39429782, 2024).
atherosclerosis (1 paper, 2025). A disease characterized by the build-up of fatty material and calcium deposition in the arterial wall resulting in partial or complete occlusion of the arterial lumen. "Six shared loci that were shared across all traits in the analysis, all with known associations with atherosclerosis (nearest genes: MAT2A, IRS1, STAG1, PVRL2, OPRL1, ARVCF)." (PMID 40313769, 2025).
autism spectrum disorder (1 paper, 2023). A spectrum of developmental disorders that includes autism, and Asperger syndrome. "For autism spectrum disorder, DGCR2, ARVCF, GNB1L, COMT, ZDHHC8, CHRNA7, and NRXN1 are candidate genes with various associated developmental defects." (PMID 37486921, 2023).
Intellectual disability (1 paper, 2024). "One of the variants, rs2531698, is an intronic variant within ARVCF, located in 2 kb upstream of the TANGO2 gene, which is associated with neurodegeneration and intellectual disability." (PMID 39429782, 2024).
mammary tumor (1 paper, 2016). "Based on these results and the fact that mILC incidence is drastically reduced in TKO tumors, we conclude that ARVCF, p0071 or δ-catenin do not play redundant roles in mammary tumor formation in TKO mice." (PMID 27411687, 2016).
microcephaly (1 paper, 2019). A congenital or acquired developmental disorder in which the circumference of the head is smaller than normal for the person's age and sex. "Our study associates disruption of Arvcf with abnormalities in the striatum (smaller), while in the Simons Simplex Collection31 we identified a de novo nonsense mutation affecting ARVCF in an ASD patient presenting with microcephaly." (PMID 31371714, 2019).
Obesity (1 paper, 2023). Accumulation of substantial excess body fat. "Recently, a rare ARVCF missense variant of unknown significance has been identified in an individual with early-onset severe obesity, suggesting that ARVCF may play an important role in the etiology of obesity." (PMID 36706759, 2023).
smoking (1 paper, 2023). "Finally, our EMIC analysis revealed that ARVCF is a causal gene for smoking addiction where we found an increased ARVCF expression can lead to an increased risk of ND." (PMID 38025780, 2023).
cancer (2 papers, 2012 to 2020). A tumor composed of atypical neoplastic, often pleomorphic cells that invade other tissues. "ARVCF gene is a member of the p120 catenin family of proteins and its over-expression has been shown to cause disruption of cell adhesion, which may facilitate cancer progression." (PMID 23248619, 2012).
neurodevelopmental disorder (2 papers, 2015 to 2019). A behavioral and cognitive disorder with onset during the developmental period that involves impaired or aberrant development of intellectual, motor, or social functions. "Interestingly, all four delta catenin proteins: ARVCF, catenin δ-1, catenin δ-2, and plakophilin-4 are implicated in ASD or neurodevelopmental disorders." (PMID 30814930, 2019).
tumor (2 papers, 2012 to 2016). "Next we determined the expression of ARVCF, δ-catenin and p0071 in the different tumor sub-types from TKO mice, which were compared to tumors from Wcre;Cdh1F/F;Trp53F/F mice." (PMID 27411687, 2016). "Therefore, it is possible that SNP rs2073743 of ARVCF may predispose patients to higher risk of refractory TGCT by inhibition of cell adhesion, which consequently causes more aggressive tumor biology." (PMID 23248619, 2012). "ARVCF, δ-catenin and p0071 showed diffuse localization patterns regardless of tumor type or p120 status." (PMID 27411687, 2016).
heart disease (1 paper, 2021). "Further potentially disease-relevant protein candidates without a known functional relation to hypertrophy, fibrosis or decompensated heart disease were SLTM, HNRNPLL, FIP1L1, RNMT, KRT18 and PUF60 and the downregulated NUDT4, GCAT, KIDINS220 and ARVCF." (PMID 34937869, 2021).
neurological disorders (1 paper, 2023). "The protein encoded by ARVCF belongs to p120ctn catenin family, which plays a significant functional role in various aspects of neuronal morphogenesis, neurodevelopmental and neurological disorders." (PMID 38025780, 2023).
ARVCF also shares sentences with these, for which no sentence is quoted: autism (2 papers); acute coronary syndrome (1); coronary artery disease (1); diseases of the larynx and vocal cords (1); Huntington disease (1); movement disorder (1); neuroblastoma (1); Parkinson disease (1); psychiatric disorder (1); viral infection (1).